AREG (amphiregulin)
Description:
Ligand of the EGF receptor/EGFR. Autocrine growth factor as well as a mitogen for a broad range of target cells including astrocytes, Schwann cells and fibroblasts.
Synonyms: AR; CRDGF; AREGB; SDGF
Tractability: Small molecule: it belongs to a druggable protein family. Antibody: its Gene Ontology location is reachable by antibodies, with high confidence; UniProt predicts a signal peptide or a membrane-spanning region. PROTAC: ubiquitination databases record sites on it; a small molecule that binds it is known.
Target class: Secreted protein
Gene: Protein-coding gene on chromosome 4 (74,444,999 to 74,455,005, forward strand). Ensembl gene ENSG00000109321.
Subcellular location: Membrane
Subcellular location (Human Protein Atlas): Mitochondria
Pathways (Reactome):
Signal Transduction: EGFR downregulation; EGFR interacts with phospholipase C-gamma; Estrogen-dependent nuclear events downstream of ESR-membrane signaling; Extra-nuclear estrogen signaling; GAB1 signalosome; GRB2 events in EGFR signaling; PI5P, PP2A and IER3 Regulate PI3K/AKT Signaling; PIP3 activates AKT signaling; RAF/MAP kinase cascade; SHC1 events in EGFR signaling; Signaling by EGFR
Vesicle-mediated transport: COPII-mediated vesicle transport; Cargo concentration in the ER; Cargo recognition for clathrin-mediated endocytosis; Clathrin-mediated endocytosis
Developmental Biology: Developmental Lineage of Mammary Gland Luminal Epithelial Cells; Developmental Lineage of Mammary Gland Myoepithelial Cells
Disease: Constitutive Signaling by Aberrant PI3K in Cancer; Inhibition of Signaling by Overexpressed EGFR
Cellular responses to stimuli: NFE2L2 regulating tumorigenic genes
Gene Ontology:
Molecular function: protein binding; receptor ligand activity; transmembrane receptor protein tyrosine kinase activator activity; epidermal growth factor receptor binding; growth factor activity
Biological process: epidermal growth factor receptor signaling pathway; ERBB2-EGFR signaling pathway; G protein-coupled receptor signaling pathway; positive regulation of cell population proliferation; cell-cell signaling; positive regulation of keratinocyte proliferation; glial cell proliferation; negative regulation of osteoblast differentiation; neuron projection development; positive regulation of phosphorylation; response to cAMP; response to glucocorticoid; response to hydrogen peroxide; response to peptide hormone
Cellular component: cell surface; extracellular region; clathrin-coated endocytic vesicle membrane; endoplasmic reticulum membrane; endoplasmic reticulum-Golgi intermediate compartment membrane; ER to Golgi transport vesicle membrane; cytoplasm; membrane; nucleus
Genetic constraint (gnomAD): Loss-of-function variants: 16 observed, 29.53 expected, observed/expected ratio (o/e) 0.54, 90% interval 0.37 to 0.82. The upper end of that interval is the gene's LOEUF score, 0.82, which puts it in group 3 of 6, group 1 being the genes least tolerant of losing a copy. Missense variants: 287 observed, 324.78 expected, observed/expected ratio (o/e) 0.88, 90% interval 0.8 to 0.97. Synonymous variants: 113 observed, 117.38 expected, observed/expected ratio (o/e) 0.96, 90% interval 0.83 to 1.12.
Homologues: Orthologues: macaque AREG (96% identical), chimpanzee AREG (88% identical), pig AREG (81% identical), dog AREG (75% identical), rabbit AREG (73% identical), mouse Areg (70% identical), rat Areg (69% identical), guinea pig AREG (65% identical), tropical clawed frog areg (35% identical). Paralogues in human: HBEGF (22% identical), BTC (13% identical), EREG (12% identical), EPGN (10% identical), TGFA (10% identical).
Diseases named in the same sentence as AREG in open-access papers:
AREG is named in the same sentence as 243 diseases in open-access papers, as found by Europe PMC text mining. Sharing a sentence is not in itself a finding about the gene and the disease. The quoted sentences say what the papers report.
breast carcinoma (101 papers, 1994 to 2025). "Numerous studies have indicated that AREG is implicated in drug resistance across various cancer cell types, such as breast cancer, liver cancer, pancreatic cancer, and colorectal cancer." (PMID 38225277, 2024). "AREG is also associated with hepatocellular carcinoma, cholangiocarcinoma, pancreatic cancer, lung cancer, and breast cancer." (PMID 37796226, 2023). "Ultimately, our novel finding that AREG mediates BPAF-induced ER-RTK crosstalk in ER+ breast cancer cells supports future studies to characterize the impact of BPAF on human ER+ breast cancer risk and to assess the safety profile of BPAF." (PMID 31059536, 2019). "In conjunction with previous studies, our data highlight AREG as a potential therapeutic target for BPAF-associated ER+ breast cancer." (PMID 31059536, 2019). "Further evidence shows that loss of AREG in breast cancer cells can stunt tumor proliferation, growth, and invasiveness in vitro and in vivo." (PMID 30367629, 2018). "This phenotype was accompanied by an increase in mRNA levels for growth factors, including amphiregulin, which is often associated with a loss of ER and increased inflammatory signaling in breast cancers." (PMID 24816718, 2014). "PRL positively interacted with E2 to further elevate several transcripts encoding growth and progression factors for breast cancer, including AREG, EREG, PTHrP and WT1." (PMID 23758962, 2013). "Expression of the Epidermal Growth Factor Receptor ligand, Amphiregulin, has been associated with estrogen receptor positive breast cancer." (PMID 24010672, 2013). "Additionally, AREG has been implicated in breast cancer progression and aggressiveness and has been identified as a key target gene for T3 in MCF-7 breast cancer cells." (PMID 39876971, 2024). "Loss of amphiregulin inhibits proliferation and invasion properties of breast cancer cells." (PMID 38460941, 2024). "We hypothesise however, that in luminal-type/ER+/LN− breast cancer, AREG expression downstream of ERα-CITED1 may be associated with an active ERα-coregulator complex that is more amenable to endocrine antagonism." (PMID 37322548, 2023). "However, AREG expression levels have been associated with disease progression of breast cancer or head and neck squamous cell carcinoma in patients receiving a combination treatment of anti-EGFRs and docetaxel." (PMID 32674321, 2020). "Higher amphiregulin expression is associated with aggressive breast cancer." (PMID 31355130, 2019). "Given this, we observed a significant increase in expression of ER target proteins, c-Myc and AREG, both of which play important roles in normal mammary gland development and breast cancer when aberrantly expressed." (PMID 40105700, 2025). "Lastly, we evaluated the effect of AREG knockdown on the tumorigenicity of T47D breast cancer cells using an orthotopic xenograft model." (PMID 40422206, 2025). "We collected blood samples from ER+- breast cancer patients to verify the correlation between E2 and AREG." (PMID 40422206, 2025). "The cell proliferation, migration, and tumorigenicity of ER+ breast cancer cells were increased by recombinant human AREG treatment." (PMID 40422206, 2025). "Secreted AREG expression in serum was meaningfully increased in breast cancer patients with high E2." (PMID 40422206, 2025). "The levels of AREG mRNA and protein expression were increased in ER+ breast cancer cell lines compared to ER- breast cancer cell lines." (PMID 40422206, 2025). "Our results also showed higher AREG mRNA expression levels in ER+ breast cancer cells than in ER- breast cancer cells." (PMID 40422206, 2025). "We found that ESR1 expression was also positively correlated with AREG expression in a variety of breast cancer cell lines." (PMID 40422206, 2025). "The purpose of this study was to elucidate the role of AREG in promoting the aggressiveness of ER+ breast cancer by activating the E2/ER signaling pathway." (PMID 40422206, 2025).
breast carcinoma (continued). "E2, as well as ESR1 expression, was positively correlated with AREG expression in breast cancer models." (PMID 40422206, 2025). "In conclusion, in this study, we focused on understanding the mechanism of autocrine loops of AREG and why EGFR+ and ER+ breast cancer is associated with poor patient prognosis." (PMID 40422206, 2025). "AREG also promotes oncogenic signaling in breast cancer, particularly in phosphatase and tensin homolog-null contexts, and can be secreted via exosomes to enhance cancer cell invasion capabilities." (PMID 40725192, 2025). "This demonstrates that the inhibition of the MAPK/ERK pathway reduces AREG gene expression induced by T3 in this breast cancer cell line." (PMID 39876971, 2024). "The epidermal growth factor (EGF) family member amphiregulin (AREG) was identified 25 years ago in the supernatant of MCF-7 human breast carcinoma cells treated with phorbol 12-myristate 13-acetate (PMA)." (PMID 38394508, 2024). "We wanted to examine if ERα-AREG signalling is also CITED1-mediated in breast cancer cells and the relatively low levels of CITED1 in MCF7s compared to other luminal-types made them ideal for development of a CITED1-overexpression model." (PMID 37322548, 2023). "AREG has been described as being highly expressed in breast cancer and facilitating tumor progression." (PMID 37604948, 2023). "Among all types of tumors, GPR81 is mainly expressed in breast cancer, especially cells positive for the estrogen receptor (ER), where it increases the production of proangiogenic amphiregulin through a PI3K/Akt/cAMP-dependent pathway." (PMID 36230479, 2022). "One study reported that ROS levels in BRCA1 and basal-like breast cancer correlated with AhR expression and this increased expression of amphiregulin (AREG), a ligand for the epidermal growth factor receptor (EGFR)." (PMID 36428667, 2022). "IPA showed that the pathways of mammary tumours, genitourinary tumours and extracranial solid tumours were strongly activated in G1 cells, in which AREG, ARL4C, and ARID5B showed the greatest contribution to activation." (PMID 35184420, 2022). "This role of AREG in TAM-stimulated cell invasion is consistent with a previous study which assessed the ability of several EGFR ligands in promoting breast carcinoma cell invasion." (PMID 34843542, 2021). "In a murine model of breast cancer to bone metastasis, OSM was demonstrated to cause the upregulation and secretion of amphiregulin (AREG), a growth factor that lead to the differentiation of osteoclasts." (PMID 34395259, 2021). "Endogenous Pparγ1 induced expression of both an EphA2-Amphiregulin and an inflammatory INFγ and Cxcl5 signaling module, that was recapitulated in human breast cancer." (PMID 33946495, 2021). "Areg (amphiregulin), a player in breast cancer proliferation, is abundant in the pubertal mammary gland and loss of Areg in mice results in stunted ductal morphogenesis." (PMID 33297495, 2020). "Whereas endocrine therapy induces suppression of amphiregulin in responsive cells, the activation of an amphiregulin/EGFR autocrine loop has been proposed to drive endocrine-resistant phenotypes in breast cancer." (PMID 33086721, 2020). "In line with this idea SASP can stimulate the proliferation of cancer cells in multiple ways including growth-related oncogenes in breast cancer and melanomas, and amphiregulin in prostate cancer." (PMID 31186408, 2019). "Particularly, we identify AREG as a critical mediator of BPAF-induced ER-RTK crosstalk in ER+ breast cancer cells." (PMID 31059536, 2019). "As AREG is an ER-targeted gene that encodes for the RTK ligand protein amphiregulin, our finding that BPAF potently upregulates AREG in ER+ breast cancer cells is novel." (PMID 31059536, 2019). "AREG as a novel target for breast cancer therapy is attractive, potentially reducing the side effects of broad EGFR inhibition while targeting breast tumor growth that is driven by AREG." (PMID 30367629, 2018).
breast carcinoma (continued). "In the studies described, we show for the first time novel functions of AREG in mammary gland development, PyMT expression, and breast cancer growth." (PMID 30367629, 2018). "In our studies, we sought to better understand the role of AREG in breast cancer using the MMTV-PyMT (PyMT) mouse model." (PMID 30367629, 2018). "In the PyMT model of breast cancer, we have shown that myoepithelial cells and growth factors AREG, EGF, and bFGF suppress PyMT expression." (PMID 30367629, 2018). "Overexpression of AREG was found in several cancers, such as ovarian cancer, breast cancer, hepatocellular cancer, and gastric cancer." (PMID 28256068, 2017). "Several EGF ligands have been implicated in breast cancer, including EGF, epiregulin (EREG), amphiregulin (AREG), heparin-bound EGF (HB-EGF) and transforming growth factor alpha (TGFα)." (PMID 26215578, 2015). "qRT-PCR was performed to assess expression levels of EREG, AREG, EGF, HB-EGF and TGFα, all of which have been implicated in breast cancer." (PMID 26215578, 2015). "Total PCBs associated with AREG, CYP19A1, ESR2, FOS, KRAS and STC2 genes; PCB 126 associated with AREG, CYP19A1, and STC2 genes and PCB 15 associated with CYP19A1, EGFR, ESR2, FOS, and IGF1 genes overlapped with 17β-estradiol, breast cancer, and endometriosis." (PMID 26512648, 2015). "Several studies have examined AREG expression in breast carcinomas by immunohistochemistry and found that AREG expression is higher in infiltrative breast carcinoma than in normal epithelium and is associated with regional lymph-node metastasis." (PMID 24587767, 2014). "We then evaluated the circulating Amphiregulin levels in women with active breast cancer (43 with ER-positive and 34 with ER-negative breast cancer) (Cohort 2)." (PMID 24010672, 2013). "Measurement of serum Amphiregulin levels lacks the necessary sensitivity and specificity for breast cancer screening in the general population." (PMID 24010672, 2013). "Specifically, fibroblast-secreted amphiregulin promoted breast cancer cell survival, whereas the chemokine CCL7 stimulated tumor cell proliferation while CCL2 promoted innate immune cell infiltration and angiogenesis." (PMID 24068959, 2013). "Amphiregulin has been found to be highly expressed by hormone therapy-resistant breast cancer cells." (PMID 23844004, 2013). "The established breast cancer relevance for AREG, WT1, and IER3 is discussed in a previous transcript profiling study." (PMID 23758962, 2013). "In this study, we showed that Monad-mediated degradation is one of the mechanisms that determine the stability of amphiregulin mRNA and that Monad-amphiregulin axis plays an essential role in the invasion of breast cancer cells." (PMID 23844004, 2013). "Serum Amphiregulin levels were quantified by ELISA from 125 cancer-free women and 114 breast cancer patients." (PMID 24010672, 2013). "In the normal rat mammary gland and inhormone-dependent rat mammary cancers, AREG has also been shown to mediate E and Psignaling through EGFR." (PMID 23705924, 2013). "The other three loci (ZNF703, INHBB, and AREG) have strong links to breast cancer, estrogen regulation, and breast development." (PMID 22747683, 2012). "Collectively, our data underscore the pivotal role of P4 and EGF signaling cross-talk as well as the impact of PRA/PRB ratio for controlling key target genes such as HBEGF and AREG involved in breast cancer development and metastasis." (PMID 23029355, 2012). "More recently, the Egln1 hydroxylase has been shown to have a Hif-independent function on amphiregulin regulation in breast carcinoma." (PMID 22905089, 2012). "In breast carcinomas, expression of GREB1 and AREG was associated with serum estradiol in all cancers and in the subgroup of estrogen receptor positive cases." (PMID 21812955, 2011).
breast carcinoma (continued). "Amphiregulin increases invasion capabilities of MCF-7 breast cancer cells, and transcriptional profiling experiments revealed that amphiregulin promotes distinct patterns of gene expression compared to EGF." (PMID 21967738, 2011). "Further studies will determine the impact of amphiregulin expression for therapy response and outcome in women with breast cancer." (PMID 21967738, 2011). "An age signature validated against two other independent breast cancer datasets proved to have >80% accuracy in discerning younger from older ER-positive breast cancer cases with characteristic differences in AREG and ESR1 expression." (PMID 17850661, 2007). "EGFR is overexpressed in a large subset of primary breast carcinomas, and EGFR ligands such as TGF-α and amphiregulin are found in 50 to 90% of primary breast carcinomas." (PMID 15987464, 2005). "Furthermore, suppressing the AREG/EGFR signaling pathway can be a fundamental therapeutic strategy for treating ER+ breast cancer when combined with classical chemotherapy." (PMID 40422206, 2025). "Additionally, we found that the levels of AREG expression were higher in ER+ breast cancer patients than in ER- breast cancer patients using the E-TABM-158 dataset." (PMID 40422206, 2025). "Thus, the in vitro or in vivo data suggest that AREG plays an important role in the tumorigenicity of ER+ breast cancer." (PMID 40422206, 2025). "Thus, we suggest that AREG directly regulates cell proliferation and migration in ER+ breast cancer cells." (PMID 40422206, 2025). "However, our results revealed that serum levels of AREG were higher in pre-menopausal breast cancer patients than in post-menopausal patients." (PMID 40422206, 2025). "Among these, AREG was the only protein that promoted the growth of ER+ breast cancer cells." (PMID 40422206, 2025). "More specifically, we cultured MDA-MB-231 breast cancer cells with conditioned medium derived from ATP-treated senescent WI-38 cells that were cultured in the presence of either NF-157 or a neutralizing antibody specific for amphiregulin." (PMID 38460941, 2024). "A role for AREG in cancer development and progression is also suggested by clinical data, indicating that AREG has prognostic utility in gastric, colorectal, non-small cell lung, and breast cancer." (PMID 38727313, 2024). "AREG mAb synergism with DNA-damaging agents was also observed in mice implanted with prostate or breast cancer cells together with AREG-expressing stromal cell counterparts, wherein an AREG mAb combined with mitoxantrone, reduced tumor volume more significantly than either monotherapy alone." (PMID 40727266, 2024). "Furthermore, AREG has been identified as a downstream effector of estrogen in ERα+ breast cancer and its expression is necessary for the growth of MCF7 xenografts." (PMID 37322548, 2023). "AREG was described as a regulator of cell growth factors in breast cancer cells." (PMID 37868614, 2023). "AREG is a predictive biomarker in the treatment of colorectal cancer and promotes the progression of cancers via the AREG/EGFR pathway in pancreatic cancer, breast cancer and ovarian cancer, suggesting that AREG may be an attractive target in HNSCC." (PMID 37106442, 2023). "A significant overexpression in estrogen-responsive genes, such as GREB1 and AREG, was observed in estrogen-receptor positive (ER+) breast cancer patients aged 45 years or younger, who had a significantly lower expression of ESR1 compared to older women (age ≥70 years)." (PMID 36685821, 2022). "The epidermal growth factor receptor (EGFR) ligand amphiregulin (AREG) is shown to be required for YAP-induced proliferation in breast cancer cells, thus suggesting that EGFR signaling is an important YAP effector, regulating both physiological and malignant cell proliferation." (PMID 34439395, 2021).